RCC2-AS1 (RCC2 antisense RNA 1)
Synonyms: LCPAT1; ENST00000439577
Gene: Long non-coding RNA gene on chromosome 1 (17,406,760 to 17,407,382, forward strand). Ensembl gene ENSG00000227751.
Diseases named in the same sentence as RCC2-AS1 in open-access papers:
RCC2-AS1 is named in the same sentence as 2 diseases in open-access papers, as found by Europe PMC text mining. Sharing a sentence is not in itself a finding about the gene and the disease.
RCC2-AS1 shares sentences with these, for which no sentence is quoted: lung carcinoma (5 papers); breast carcinoma (2).